HNF1B (HNF1 homeobox B)
Diseases named in the same sentence as HNF1B in open-access papers (continued):
Sharing a sentence is not in itself a finding about the gene and the disease.
tumor (continued). "To determine whether any of the known, significant PC risk SNPs correlated with HNF1B expression levels, we genotyped each SNP in 65 British patients, and compared these to mRNA levels of HNF1B in tumor tissue and, where possible, matched non-tumor tissue from the same individuals." (PMID 27732966, 2016). "Inour case, the tumor cells were negative for thyroglobulin and TTF-1 but positive forPAX8 and HNF1β." (PMID 39700333, 2024). "These TFs included tumor-promoting ZKSCAN1 from the open chromatin regions of metastases patients and tumor suppressor HNF1B from the open chromatin regions of non-metastases patients." (PMID 34439749, 2021).
cancer (73 papers, 2006 to 2026). A tumor composed of atypical neoplastic, often pleomorphic cells that invade other tissues. "Single nucleotide polymorphisms (SNPs) of HNF1B have been identified and associated through genotyping arrays with cancer development." (PMID 36672242, 2023). "Here our study reported a germline-somatic association of TMPRSS2-ERG with this cross-cancer locus of 17q12/HNF1B, mechanistically and biologically implicating PCa risk and progression." (PMID 36443337, 2022). "Yet, the mechanistic effects and underlying biology of the 17q12/HNF1B remain elusive for all of these associated cancer types." (PMID 36443337, 2022). "In‐depth characterization of HNF1B and its splice variants are warranted to compliment its ever‐growing importance in different cancers." (PMID 33580750, 2021). "Overexpression of HNF-1β has been implicated in tumour progression in cancers such as clear cell carcinoma of the ovary, liver, pancreas, kidney, endometrium, and prostate." (PMID 34680055, 2021). "HNF1B expression is associated along with heterogenous immune cell infiltration levels in distinct cancers." (PMID 33580750, 2021). "The results showed that HNF1B is dysregulated in various cancers and associated with the differential overall survival of cancer patients." (PMID 33173410, 2020). "According to these results, our study found that HNF1B mutations occurred widely in human cancers and that the most common type is missense mutations." (PMID 33173410, 2020). "In the present study, we evaluated expression and mutations of HNF1B in different types of cancer from The Cancer Genome Atlas (TCGA) database." (PMID 33173410, 2020). "Our study showed that HNF1B expression is associated with diverse immune cell infiltration levels in different cancers." (PMID 33173410, 2020). "Overexpression of HNF1β has been observed in different types of human cancer and is associated with the poor prognosis of patients with cancer." (PMID 32863913, 2020). "Multiple studies have examined the relationship between the hepatocyte nuclear factor-1 beta (HNF1B, formerly known as TCF2) locus (on chromosome 17q12) and cancer risk." (PMID 30053805, 2018). "In recent years, the expression of HNF-1β has been reported to be associated with risk for a variety of cancers." (PMID 28684878, 2017). "Based on the identification of several cancer-associated SNPs within HNF1B, we aimed to define the function of HNF1B in this context." (PMID 27732966, 2016). "Recent studies have shown that expression of HNF1β is associated with cancer risk in several tumors, and HNF1β plays an important role in tumorigenesis." (PMID 26464794, 2015). "Analyses by us and others indicate that HNF1B is the target gene for genetic risk associations with cancer in this region, although the mechanism of regulation mediated by risk SNPs is not necessarily the same between cancer subtypes." (PMID 25378557, 2015). "In tumors, mutations and epigenetic inactivation of the HNF-1β gene has been shown to be involved in the development of several cancer." (PMID 25884453, 2015). "Various analyses have been undertaken to assess the relationship between HNF1B locus cancer risk SNPs and altered regulation of HNF1B mRNA expression." (PMID 25378557, 2015). "More recently, genetic variants in the HNF1B were implicated in the prostate and endometrial cancer risks." (PMID 24386569, 2013). "In a collaborative analysis, we collected data from GWAS of cancer phenotypes for the frequently reported variants of HNF1B, rs4430796 and rs7501939, which are in linkage disequilibrium (r2 = 0.76, HapMap CEU)." (PMID 20526366, 2010). "The role of HNF1B splice variants needs to be well defined in cancer and a better understanding of the mechanisms might lead to a breakthrough in therapeutic applications." (PMID 33580750, 2021).
cancer (continued). "Moreover, the expression of HNF1B has been associated with immune cell infiltration which in turn influences the prognosis of immune cells in some cancers highlighting HNF1B as a potential immunotherapeutic target." (PMID 33580750, 2021). "The distinct prognostic value of HNF1B may be caused by the different mutations and interactions between HNF1B and other genes in different types of cancers." (PMID 33173410, 2020). "HNF1b is a transcription factor which is associated with the development of many cancers." (PMID 32492656, 2020). "Moreover, HNF1B expression is associated with many immune cell infiltration levels and influences the prognostic prediction of immune cells in some kinds of cancers." (PMID 33173410, 2020). "Moreover, HNF1B is associated with the level and prognosis prediction of immune cells in some kinds of cancers." (PMID 33173410, 2020). "We applied the cBio cancer genomics portal to explore the mutations of HNF1B in different cancers." (PMID 33173410, 2020). "Moreover, the EPIC algorithm analysis showed that HNF1B was significantly associated with NK cell and cancer-associated fibroblasts in cancer." (PMID 33173410, 2020). "HNF1B showed many mutation forms and high mutation levels in different cancer types." (PMID 33173410, 2020). "Moreover, we explored the association of HNF1B with immune cell infiltration levels and their prognostic values in cancer patients." (PMID 33173410, 2020). "In contrast to somatic HNF1B mutations, much more information is available about the significance of HNF1B SNPs and their association with either an increased or decreased risk of the development of several cancers." (PMID 33051485, 2020). "Furthermore, we explored the relevant human genome location and the association between certain genes and HNF1B in human cancer based on a regulome explorer." (PMID 33173410, 2020). "HNF1B is involved in the regulation of cell proliferation, and genetic variation in HNF1B might modulate the risk of cancer." (PMID 30053805, 2018). "However, fine-mapping studies have revealed a complex genetic architecture of the HNF1B locus, demonstrating that variants of HNF1B and the direction of their effects differ between cancer types." (PMID 30053805, 2018). "However, loss of ARID1A, along with low-level HNF-1b expression, was common in patients with cancer recurrence and was correlated with late-stage and worse survival outcome." (PMID 29743986, 2018). "Evidence to date indicates that cancer risk may be mediated via genetic or epigenetic effects on HNF1B gene expression." (PMID 25378557, 2015). "However, the potential pathogenic mechanisms of HNF1β in cancer and regulatory mechanisms in stem cells are still less understood." (PMID 26464794, 2015). "Prior studies have linked HNF1B to cancer, though sometimes with contradictory roles." (PMID 24040285, 2013). "Based on these results, HNF1B may be a good potential diagnostic biomarker for different cancers." (PMID 33173410, 2020). "HNF1B mutations are widely observed in tumors and interact with different genes in different cancer types, which may be the cause of the distinct prognostic values in cancers." (PMID 33173410, 2020). "Our findings highlight the multiple, small blocks of linkage disequilibrium within HNF1B, and may explain the complex associations observed at this locus between different risk SNP alleles, HNF1B expression and promoter methylation depending on cancer or histological subtype." (PMID 27732966, 2016). "In ovarian clear cell carcinoma and endometriosis, high levels of HNF-1β induce G2 cell cycle arrest and survival of cancer cells through Chk1 activation, following genotoxic stress induced by bleomycin, a cytotoxic antibiotic." (PMID 41009395, 2025). "HNF1B is a hepatocyte-specific TF expressed in several cancers, and the reduction of HNF1B levels in CCC cell lines has been shown to cause apoptosis." (PMID 39149248, 2024).
cancer (continued). "We first evaluated the expression profiles of HNF1B across 31 cancer types using RNA-seq data of The Cancer Genome Atlas (TCGA) and found that HNF1B was highly expressed in approximately top 25% of cancer types including PCa." (PMID 36443337, 2022). "HNF1B contributes to resistance against anti-cancer agents through glutathione synthesis and the Warburg effect." (PMID 34067626, 2021). "Under hypoxia and acidosis, HNF1B can modify and adapt cancer cells to survive through a process between gluconeogenesis and glycolysis, commonly known as the Warburg effect." (PMID 33525614, 2021). "Fine‐mapping analysis has revealed an complex genetic architecture at HNF1B gene loci, relating to different cancer types." (PMID 33580750, 2021). "The presence of several STAT3, and a single HNF-1β TFBS in the NNMT promoter region suggest a mechanism for the observed induction of NNMT expression in cancer." (PMID 34680055, 2021). "As overexpression of HNF1B and SOD2 confers resistance to oxidative stress in cancer cells, OCCCs possess strong resistance to oxidative stress caused by cancer treatments such as chemotherapy." (PMID 33525614, 2021). "In this review, the role of HNF1B in different cancers has been discussed along with the role of its splice variants, associated functions and the emerging role of its epigenetic regulation." (PMID 33580750, 2021). "Despite the great knowledge of mutations in HNF1B in MODY, few studies have highlighted the role of mutations in cancer." (PMID 33580750, 2021). "The aim of this study was to explore the significance of HNF1B in human cancer by an integrative analysis of online databases." (PMID 33173410, 2020). "In conclusion, our study found that HNF1B mRNA is dysregulated in various cancers and that the differential expression of HNF1B indicates different prognoses." (PMID 33173410, 2020). "Based on the TCGA dataset, we evaluated the correlation of HNF1B with levels of immune cell infiltration in cancer from TIMER." (PMID 33173410, 2020). "Given the results of the present study, the function of the miR-375-3p/HNF1β axis deserves further investigation in different types of cancer." (PMID 32863913, 2020). "To determine the potential value of HNF1B in predicting the overall survival of cancer patients, we constructed Kaplan-Meier survival curves." (PMID 33173410, 2020). "The correlation between HNF1B expression and overall survival of cancer patients was further validated based on the Kaplan-Meier plotter." (PMID 33173410, 2020). "The results showed that HNF1B expression in various cancers was obviously different from that in normal tissues." (PMID 33173410, 2020). "Recent researches revealed that DNA methylation mediated HNF1B silencing frequently occurs in many cancers." (PMID 31636385, 2020). "Survival analysis revealed that HNF1B expression indicated distinct overall survival rates of cancer patients." (PMID 33173410, 2020). "A previous study demonstrated that HNF1β is targeted by miRNAs and negatively modulated in cancer cells." (PMID 32863913, 2020). "HNF1B promoter methylation was significantly higher among the carcinoma cases of a higher stage (T3 + 4) in comparison to the lower stage (T1 + 2), and also with the higher Gleason score (intermediate and high grade) in comparison to the lower grades." (PMID 32873863, 2020). "While the CRC mapper output consisted of multiple TFs, intersection with transcriptomic and functional genomic datasets highlighted the importance of PAX8 and HNF1B in cancer cells proliferation." (PMID 31431624, 2019). "HNF1B can modify and adapt cancer cells to survive under hypoxia and acidosis in a process facilitated by increased glucose consumption and glycolysis, commonly known as the Warburg effect." (PMID 31366141, 2019).
cancer (continued). "circ‐TTBK2 increases HNF1β expression in cancer, acting as miR‐217 sponge, and as a result, miR‐217 cannot negatively regulate HNF1β by targeting its 3′‐UTR." (PMID 30719845, 2019). "The expression of HNF-1B in carcinomas of kidney and Müllerian origin also indicates its pathophysiological role in these organs." (PMID 30065837, 2018). "To confirm hypermethylation in the HNF1B gene, we analyzed 124 samples (64 cancer samples and 60 control samples)." (PMID 28241454, 2017). "To identify biological pathways regulated by HNF1B in the context of cancer, we generated stable cell lines over-expressing HNF1B." (PMID 27732966, 2016). "Alternatively, it has been postulated that HNF1B is able to influence cancer cell survival by promoting the activation of NFkB pathway or through the inhibition of mitochondria-associated apoptotic signals." (PMID 27437873, 2016). "Usually, ARID1A mutation is an early event in neoplastic transformation and it is present both in carcinoma and preneoplastic tissue whilst HNF1B is usually found only in cancer tissue." (PMID 25885815, 2015). "Undifferentiated carcinomas showed expression of HNF-1β in 2/14 cases (14.3%), CEA in 8/14 cases (57.1%), p16 in 14/14 cases (100%), hormone receptors in 0/13 cases (0%), p63 in 7/14 cases (50%), p40 in 5/14 cases (35.7%), and D2-40 in 1/14 cases (7.1%)." (PMID 25884453, 2015). "Here, we set out to explore more broadly the relation between HNF1B and carcinomas with clear cell histology." (PMID 24040285, 2013). "Notably, HNF1B shows the highest expression in ccRCC compared to other cancers across both databases." (PMID 39915461, 2025). "The critical master regulators of CCC cancer cells were HNF1B and SOX4." (PMID 39149248, 2024). "Moreover, the group also demonstrated HNF1B mRNA dysregulation in different cancers that lead to differential expression of HNF1B leading to distinct prognosis." (PMID 33580750, 2021). "HNF1B could play critical functions in proliferation, metastasis, apoptosis, and linked to EMT pathway in several cancers 46-49." (PMID 34475987, 2021). "As mentioned under the headings “Molecular characteristics in OCCCs related to anti-oxidative pathway” and “Oxidative stress and cancer stemness of OCCC,” molecules conferring oxidative stress resistance, including HNF1B, SOD2, and RDH10, are deeply implicated in therapeutic refractivity." (PMID 33525614, 2021). "Tsuchiya and colleagues hypothesized that ovarian CCC might be a wholly distinct entity apart from epithelial ovarian carcinoma and that HNF1B over-expression in these cancers was a contributing factor." (PMID 34150416, 2021). "Moreover, recent research has revealed that HNF1B promotes the dedifferentiation of cancer stem-like cells (CSCs) via activation of the Notch pathway and enhancing the invasive potential and epithelial–mesenchymal transition in cancer cells." (PMID 33525614, 2021). "Altogether, the methylation patterns in HNF1B may be used as prognostic predictors, highlighting the value of performing a pan‐cancer methylation study in a large cohort of patients." (PMID 33580750, 2021). "In conclusion, HNF1B plays a significant role in cancer and may be a potential target for cancer immunotherapy." (PMID 33173410, 2020). "We used the UALCAN database to analyze the expression of HNF1B in different types of cancer." (PMID 33173410, 2020). "HNF1B levels in cancer tissues and in normal tissues were compared based on data from the TCGA." (PMID 33173410, 2020). "HNF1B has been reported to frequently undergo silencing in various cancer types." (PMID 31636385, 2020).